BDP1 (BDP1 general transcription factor IIIB subunit)
Diseases named in the same sentence as BDP1 in open-access papers (continued):
Sharing a sentence is not in itself a finding about the gene and the disease.
serous ovarian carcinoma (continued). "However, larger clinical studies are warranted to evaluate the clinical use of BDP1 as a predictive biomarker in serous ovarian cancer, especially by stage." (PMID 36305848, 2023). "At twelve‐month relapse‐free survival, in patients treated with taxane, BDP1 expression significantly decreased (p = 0.0059), and the ROC analysis (p = 8.4 × 10−04, AUC = 0.654) suggest BDP1 may be of predictive value in patients with serous ovarian cancer." (PMID 36305848, 2023). "At twelve‐month relapse‐free survival, in patients treated with platin, BDP1 expression significantly decreased (p = 0.0014), and the ROC analysis (p = 7.6 × 10−05, AUC = 0.663) suggest BDP1 could be of clinical relevance as a predictive biomarker in serous ovarian cancer." (PMID 36305848, 2023). "Thus, we investigated BDP1 expression in response to common serous ovarian cancer chemotherapies." (PMID 36305848, 2023). "Finally, BDP1 may have clinical applications to predict serous ovarian cancer response to platin and taxane, comparable to previously identified biomarkers of serous ovarian cancer." (PMID 36305848, 2023). "Together, these data suggest that only BDP1 of the TFIIIB complex has expression correlating with stages II, III and IV in serous ovarian cancer which interestingly, is similar to BRCA1 and BRCA2, established drivers of serous ovarian cancer." (PMID 36305848, 2023). "Using in silico analysis, the data suggests that BDP1, a subunit of the RNA polymerase III specific transcription factor TFIIIB, could be of clinical relevance as a predictive biomarker in serous ovarian cancer." (PMID 36305848, 2023).
skin cancer (1 paper, 2023). "Specifically, the TFIIIB subunits TBP, BRF1, BRF2, and BDP1 are altered in a variety of human cancers, including breast, blood, colorectal, cervical, esophageal, liver, lung, prostate, and skin cancers." (PMID 37801436, 2023).
triple-negative breast carcinoma (1 paper, 2022). An invasive breast carcinoma which is negative for expression of estrogen receptor (ER), progesterone receptor (PR), and human epidermal growth factor receptor 2 (HER2). "BDP1 has been mapped to cytogenetic band 5q13.2 and deletions of chromosome 5q1323 have been identified in poorly differentiated IDC and deletions of chromosome 5q13-14 have been associated with triple-negative breast cancer (TNBC) and poor prognosis." (PMID 35406430, 2022).
cancer (18 papers, 2008 to 2025). A tumor composed of atypical neoplastic, often pleomorphic cells that invade other tissues. "The gene BDP1 (B Double Prime 1) plays a role in cancers but is less known in N.B. Thus, we conducted this study to investigate the value of BDP1 mutations in N.B. prognosis." (PMID 34943600, 2021). "BDP1 could potentially display both oncogenic and tumor‐suppressing function that is dependent on its mutational status and can vary based on the unique mutational profile of the cancer." (PMID 36305848, 2023). "Decreased BDP1 expression correlated with poor clinical outcomes (n = 295 samples): a metastatic event at three years (p = 7.79 × 10−7) and cancer reoccurrence at three years (p = 4.81 × 10−7) in IDC." (PMID 35406430, 2022). "To offer a clarification, we have drawn a schematic diagram to illustrate the timeline of nomenclature and the difference between PTPN18 and BDP1 and their perspectives in cancer involvement, as per Professor Schramm’s suggestion." (PMID 35328170, 2022). "Together, these recent studies suggest a detailed analysis of BDP1 alterations in human cancers is warranted." (PMID 35406430, 2022). "This could potentially account for the ability of cancers with BDP1 homodeletions to continue with RNA pol III transcription in its absence as these regulators would have direct interaction with an already formed BRF1‐TBP complex." (PMID 36305848, 2023). "However, studies that determine whether BDP1 is altered in human cancers and clinically relevant are limited." (PMID 35406430, 2022). "However, few studies investigate the TFIIIB subunit BDP1 in cancer." (PMID 35406430, 2022). "The expression profiles of BDP1, CLEC11A, and ID3 genes in cancer cells were detected using qRT-PCR technology." (PMID 40607387, 2025). "Recently, the BDP1 subunit of TFIIIB, has been identified as altered in human cancers." (PMID 36305848, 2023). "Bdp1 is overexpressed in cells transformed by papovaviruses, but changes in expression levels in specific human cancer types have not been determined." (PMID 21518452, 2011). "The TFIIIB BDP1 subunit is not well characterized in human cancer." (PMID 35406430, 2022).
tumor (8 papers, 1995 to 2023). "This decreased expression of BDP1 by a larger oncogenic regulatory network could result in its inability to carry out its tumor suppressing capabilities." (PMID 36305848, 2023). "Bdp1 is a protein coding gene found in TFIIIB that can regulate JNK1 expression in c-jun N-terminal kinases (JNKs), which displays both oncogenic and tumor suppressor properties." (PMID 33947955, 2021).
BDP1 also shares sentences with these, for which no sentence is quoted: glioblastoma (2 papers); infection (2); lung carcinoma (2); cerebellofaciodental syndrome (1); cervical cancer (1); Epstein-Barr virus infection (1); Hearing impairment (1); Intellectual disability (1); leukemia (1); retinoblastoma (1); serous carcinomas (1); spinocerebellar ataxia type 17 (1); squamous cell carcinomas of the lung (1); thyroid cancer (1).